C1QA (complement C1q A chain)
Diseases named in the same sentence as C1QA in open-access papers (continued):
Sharing a sentence is not in itself a finding about the gene and the disease.
tumor (continued). "We then analyzed single-cell RNA sequencing data from patient tumors and novel single-cell RNA sequencing data from liver metastases and identified macrophages expressing high levels of C1QA, C1QB, and TREM2 in both primary tumor and metastases." (PMID 33782087, 2021). "The CIBERSORT algorithm was applied to analyze the proportions of tumor-infiltrating immune subsets to further confirm the correlations between the TME and C1qA, C1qB, and C1qC expression levels." (PMID 34079754, 2021). "On the other hand, gene expression analyses confirmed that proteins related to the complement activation, such as C1QA, SERPING1, A2M, ITGAM and ITGB2, were significantly overexpressed in P3 tumours, compared to P1 and P2 subtypes." (PMID 31560832, 2019). "The levels of eight genes (SPI1, RNASE6, C1QB, C1QC, CSF1R, C1QA, TBC1D2, and ATP6V0E1) expression were higher in tumor samples from UALCAN." (PMID 32038997, 2019). "Furthermore, several other marker genes that are known to support tumor growth and creating an immune suppressive environment like IL6, IL10, C1QA, interleukin‐1 receptor antagonist (IL1RN), and KYNU were highly expressed in our Tri culture condition." (PMID 40056038, 2025). "Significantly reduced C1qa expression, but not C1qb and C1qc expression, was observed in both MPE and tumor tissue of KO mice, indicating effective C1qa disruption in C1qa-/- mice." (PMID 39664577, 2024). "The specific role of C1QA in IDC may be related to the interaction between the immune system and the tumor microenvironment." (PMID 38627939, 2024). "Furthermore, SPP1+ Mφ, cycling Mφ, and DCs exhibited significantly higher content in tumors, while C1QA+ and VCAN+ Mφ were reduced in tumor samples in both the LIHC and LIRI HCC cohorts." (PMID 39691723, 2024). "We found that the expression of FABP4 and C1QA were significantly higher in tumor tissues (T) and lymph nodes (LN) in MPR than in non-MPR patients." (PMID 39353883, 2024). "This is in agreement with our own results, where upregulation of C1QA, C1QC, and CFHR2 in newly diagnosed PCa patients is suggestive of the involvement of tumour inflammatory microenvironment, which may act as a mediator of tumour progression and angiogenesis." (PMID 36831393, 2023). "Based on these results, we can speculate that C1QA, C1QB, and C1QC play key roles in immune cell infiltration in the tumour microenvironment of SKCM." (PMID 36110204, 2022). "This was a consequence of the decreased activation of the tumor suppressor WW domain containing oxidoreductase (WWOX), due to the lack of (neuT-C1KO) or decreased (neuT-C3KO) deposition of C1qA molecules in the tumor microenvironment." (PMID 35203439, 2022). "While in all pVAX-vaccinated mice TUBO cells gave rise to a palpable growing tumor, 100% of RHuT-vaccinated animals, regardless of the presence or absence of perforin, C1qA or C3 molecules, were protected." (PMID 35203439, 2022). "For example, genes related to the GO term “components of complement,” such as C1QA, C1QB, and C7, may promote tumorigenesis in cells within the tumor microenvironment." (PMID 34557425, 2021). "Although these results are encouraging, the tumour immune infiltration relationship between C1QA, C1QB, C1QC, and SKCM has not been established, and the expression, mechanism of action, and prognostic significance of complement components in SKCM require further exploration." (PMID 36110204, 2022). "The transcription levels of C1QA, C1QB, and C1QC were analysed based on pan-cancer data in GEPIA to observe whether there were significant differences in their expression among common tumour types." (PMID 36110204, 2022). "Therefore, we speculated that the high expression of C1QA, C1QB, and C1QC may play a dual regulatory role through anti-tumour immunity and the induction of cancer cell apoptosis." (PMID 36110204, 2022).
cancer (22 papers, 2012 to 2025). A tumor composed of atypical neoplastic, often pleomorphic cells that invade other tissues. "M-E4BP4 showed increased expression of anti-inflammatory genes such as Retnla, IL10, and C1qa, and Ccl5, which is involved in immune escape of cancer, and decreased expression of pro-inflammatory genes such as Txnrd1, Odc1, Mmp1232,36–40." (PMID 38714733, 2024). "Targeting C1QA and its regulatory pathway may, therefore, represent a promising therapeutic strategy in cancer." (PMID 41171372, 2025). "In addition, cancer-cell-intrinsic inflammatory tumor subclusters also showed an upregulation of C1R (log2FC = 0.86), C1S (log2FC = 0.46), and C3 (log2FC = 0.48), while the corresponding macrophages showed an upregulation of C1q genes (C1QA, C1QB, C1QC)." (PMID 36973268, 2023). "Consistently, previous studies have shown that SPP1, APOE, C1QA, C1QB, and C1QC are significantly elevated in the plasma of patients with cancer." (PMID 37187751, 2023). "We then performed a survival analysis of these differentially expressed cancers using the TIMER database and found that in SKCM, the expression levels of C1QA, C1QB, and C1QC were significantly correlated with OS." (PMID 36110204, 2022). "We have previously shown that, in the neuT transgenic mouse model, C1qA induces the activation of the tumor suppressor WWOX, which downregulates Her2 expression, thus limiting cancer growth." (PMID 35203439, 2022). "In conclusion, the current study showed that C1QA, C1QB, and C1QC were highly expressed in a variety of cancers, especially in SKCM, which overexpressed these three complement components and predicted better survival prognosis." (PMID 36110204, 2022). "Complement C1Q is composed of C1QA, C1QB, and C1QC and is involved in the occurrence and development of many malignant tumours." (PMID 36110204, 2022). "In the present study, we used the GEPIA database to conduct pan-cancer analysis on the transcription levels of C1QA, C1QB, and C1QC and screened out the cancer types with the differential expression of these three genes." (PMID 36110204, 2022). "The C1QA, C1QB, and C1QC genes were either over-expressed, or downregulated depending on the type of carcinoma investigated, as compared to their normal tissue counterparts." (PMID 31130944, 2019). "The expression of C1QA, C1QB, and C1QC genes was analyzed between different carcinoma and normal tissue counterparts using the Oncomine database." (PMID 31130944, 2019). "Similarly, NKG7, ARHGAP9, C1QA, and CD53 were accurately predicted in 15/28 datasets (R = 0.38–0.46 for the various cancer types)." (PMID 32747659, 2020). "Bone marrow (BM) chimeras between C1qa−/− and WT mice identify non-BM-derived cells as the main local source of C1q that can promote cancer cell adhesion, migration and proliferation." (PMID 26831747, 2016). "We also determined that TREM2+ TAMs highly expressed soluble factors such as SPP1, APOE, C1QA, C1QB, and C1QC, which suggested that this TREM2+ TAMs subset may be exocrine or paracrine for establishing the microflora critical for cancer cell invasion and the metastasis environment." (PMID 37187751, 2023).
infection (20 papers, 2012 to 2025). The state of being infected such as from the introduction of a foreign agent such as serum, vaccine, antigenic substance or organism. "To determine if there is an alteration in synaptic pruning activity between infection routes, we assessed the gene expression of key synaptic pruning markers C1qa and CD68, markers linked with ‘eat-me signals’." (PMID 35898505, 2022). "RNA sequencing data revealed a distinct pattern of gene expression during infection: Cd209a expression decreased progressively, whereas C1qa and C1qb expression increased consistently." (PMID 40170749, 2025). "Most cell subsets had elevated scores after FA-S infection, especially three subclusters of macrophages (Macro-C1qa, Macro-Saa3, and Macro-Ifit1), indicating that these cells are the main source of the inflammatory cytokine storm." (PMID 36566328, 2022). "Depleting Kupffer cells and other macrophages using clodronate liposomes prior to Ad5 administration led to a reduction in C1qa levels, both upon Ad5 infection as well as 48 h after administration of clodronate liposomes." (PMID 30926239, 2019). "Our data show that infection was accompanied by the up-regulation of c1qa and ptx3 as well as the down-regulation of mbl2." (PMID 27100179, 2016). "Two C1qA chain transcripts showed a twofold downregulation by the infection." (PMID 41398915, 2025). "Myeloid dendritic cells in dormant infections also showed notable differences in mRNA expression, affecting neutrophil recruitment (C1QA, C1QB, ITGAM), immune checkpoint regulation (IFITM2, IFITM3, CST7, THBS1), and T-cell response (VISIG4, V-set immunoglobulin domain containing 4)." (PMID 39563367, 2024). "C1qa expression was also not markedly altered by a 24 hr oral infection with the intestinal pathogenic bacterial species Salmonella Typhimurium." (PMID 37159507, 2023). "Two weeks after infection, C1q (C1qa) and C3 (C3) expression increased, as suggested previously." (PMID 33613523, 2020). "At 48 h of infection, the expression of c1qa and ptx3 was significantly induced in WT animals." (PMID 27100179, 2016). "However, viral titers remained high through 10 days post infection in C1qa−/−, and Bf−/− mice." (PMID 24740152, 2014). "Next, involvement of complement genes vital in phagocytosis (C1QA, C1QB, C1QC, C1R), which play a central role in immunity, response to infection, as well as synaptic pruning, further implicate the involvement of the immune system in ASD." (PMID 36590292, 2022). "When assessing signature synaptic pruning markers, C1qa and CD68, we detected an increase in gene expression persistent through the course of infection." (PMID 35898505, 2022).
neurodegenerative disease (12 papers, 2014 to 2025). A disorder of the central nervous system characterized by gradual and progressive loss of neural tissue and neurologic function. "Normal aging is associated with an increase in C1q protein (encoded by C1QA), particularly in certain regions of the brain that are especially prone to degenerative diseases related to aging." (PMID 27536236, 2016). "C1qa protein increases with aging in mouse and human brains in regions associated with neurodegenerative disease, whereas C1qa-deficient mice have less cognitive and memory loss." (PMID 24804771, 2014). "The complement cascade, of which C1qa is a component, controls astrocytic synapse elimination, especially in mouse models of neurodegenerative disease." (PMID 40948563, 2025). "The relevance of microglial activation of neurotoxic astrocytes in neurodegenerative disease was substantiated whereby genetic deletion of Il1a, Tnf and C1qa produced strong neuroprotective and disease-modifying outcomes in a SOD1G93A mouse model of ALS, including a 54% extension to survival." (PMID 38317225, 2024).
neurological disease (4 papers, 2020 to 2022). "The serum complement subcomponent C1q's C-chain or B-chain polypeptides, which are crucial in the regulation of the complement system and have significant effects on neurological diseases, are encoded by the genes C1QA or C1QB." (PMID 36703641, 2022). "The proteins encoded by C1QA and C1QB belong to the C1q family, whose members are the first components of the complement pathway and are involved in complement system regulation and play crucial roles in neurological disorders." (PMID 35221911, 2022). "Increased expression of C1qa does not appear to contribute to NPC1 neuropathology since neurological disease progression is not altered in Npc1−/−:C1qa−/− double mutant mice." (PMID 32731618, 2020).
Bacterial Infections (2 papers, 2021 to 2023). "C1qa, a subunit of complement C1q, indicates that the bacterial infection leads to an increase in its gene expression." (PMID 36906641, 2023).
C1QA also shares sentences with these, for which no sentence is quoted: gastric cancer (3 papers); depression (2); glomerulonephritis (2); lung adenocarcinoma (2); pertussis (2); acute coronary syndrome (1); adenocarcinoma (1); age (1); allergic rhinitis (1); aplastic anemia (1); autoimmune disease (1); brain cancer (1); cardiovascular disease (1); clear cell renal cell carcinoma (1); complement deficiency (1); esophageal cancer (1); female reproductive diseases (1); fungal infection (1); hemangiopericytoma (1); Hepatitis (1); hyperopia (1); immune deficiency (1); infectious disease (1); inherited thrombocytopenia (1); leiomyoma (1); leukemia (1); liver cancer (1); mantle cell lymphoma (1); mesothelioma (1); metastatic melanoma (1).
A further 22 diseases each share a sentence with C1QA in 1 paper.